MIR1255A (microRNA 1255a)
Synonyms: hsa-mir-1255a; MIRN1255A
Gene: MicroRNA gene on chromosome 4 (101,330,302 to 101,330,414, reverse strand). Ensembl gene ENSG00000221265.
Homologues: Orthologues: chimpanzee MIR1255A (100% identical). Paralogues in human: MIR1255B2 (42% identical).